TYMS (thymidylate synthetase)
Diseases named in the same sentence as TYMS in open-access papers (continued):
Sharing a sentence is not in itself a finding about the gene and the disease.
cancer (continued). "Whether IDH1/2 follows a similar strategy to ACO1 or TYMS, and whether it plays key roles in cancer development will be important to explore." (PMID 29216518, 2018). "Inhibition of TYMS by treatment with cancer chemotherapy drug 5-FU (5-Fluorouracil) results in accumulation of FdUMP, which might subsequently lead to increased levels of fluoro-deoxyuridine triphosphate (FdUTP)." (PMID 29100421, 2017). "Over-expression of TYMS protein has been detected in various human carcinomas including CRC." (PMID 29088787, 2017). "In brief, TYMS genotype variations present a dilemma in 5-FU-driven cancer therapy- overexpression leads to decreased drug sensitivity and poor prognosis, while underexpression leads to the manifestation of toxic drug effects that may halt therapy altogether." (PMID 27774364, 2016). "TYMS genotype variations present a dilemma in 5-FU driven cancer therapy - overexpression leads to decreased drug sensitivity and poor prognosis while underexpression leads to the manifestation of toxic drug effects that may halt therapy altogether." (PMID 27774364, 2016). "Several studies performed on other cancer types have proposed that high-level TYMS expression may predict success of 5-FU based chemotherapy." (PMID 25762627, 2015). "The TYMS 6ins allele was also associated with a higher risk of HFS >1 (P=0.011) and HFS >2 (P=0.003) in the univariate analysis, although these associations disappeared after adjusting for sex, hospital, and type of cancer." (PMID 25691056, 2015). "Similarly, Gemcitabine(DB00441) inhibits thymidylate synthetase, leading to inhibition of DNA synthesis and cell death, is indicated for the treatment of advanced cancers." (PMID 25738841, 2015). "This could confirm previous studies, which indicate a possible stimulatory effect on cancer cells resulting from folic acid fortification, which increases TYMS activity." (PMID 25978957, 2015). "Elevated TYMS level in cancer cells is considered to contribute to multidrug resistance." (PMID 25669981, 2015). "The most significantly upregulated microRNA in the simvastatin-treated MDA-MB 231 cells from our study was microRNA-612, which is known to reduce stemness and to relieve drug resistance to cisplatin and 5-fluorouracil, possibly by targeting TYMS in cancer cells." (PMID 25978957, 2015). "Thus, it is likely that fast growing and genetically unstable cancer cells are more dependent on TYMS function than normal cells." (PMID 21365010, 2011). "Therefore, the decrease in TYMS expression limits cell proliferation and cancer growth." (PMID 38542079, 2024). "In the present study, we correlated TYMS expression with the previously reported invasive capacity of particular MPM cell lines (a correlation coefficient 0.84) as TYMS expression corresponds with the stage of cancer development and epithelial-to-mesenchymal transition process." (PMID 37894370, 2023). "Collectively, these studies demonstrates that the TYMS level in tumor tissues may be a useful marker to predict the postoperative OS of cancer patients, and chemoradiotherapy after surgery could significantly improve the prognosis of cancer patients with high TYMS expression." (PMID 37682862, 2023). "MiR-197-3p is down-regulated in CRC and GC, where it targets TYMS and MTDH, which encodes a protein also involved in TYMS induction and PTEN repression, while in NSCLC and BRCA miR-197-3p is up-regulated because it also targets suppressor genes that are important in these cancers." (PMID 35922756, 2022). "However, how TYMS levels are regulated in cancer is not yet well understood." (PMID 34454516, 2021). "However, scientists and clinicians have further found that 5-FU treatment could also acutely result in the abnormal expression of TYMS in cancer cells." (PMID 34947902, 2021).
cancer (continued). "5-FU inhibits the nucleotide synthetic enzyme thymidylate synthase (TYMS) and incorporates its metabolites into DNA and RNA, which leads to the inhibition of the DNA synthesis and the disruption of RNA processing and post-transcriptional modification in cancer cells." (PMID 31744051, 2019). "Thus, the TYMS enzyme has been of interest as a target for cancer chemotherapeutic agents." (PMID 25978957, 2015). "For the polar aqueous fraction, the hub proteins obtained by evaluating the overexpressed genes in the three types of cancer (BRCA, COAD, and LUAD) were TYMS, CDKN1, TOP2A, AURKA, and TK-1." (PMID 40430485, 2025). "The expression levels of TYMS, DHFR, and SLC19A1 were significantly higher in cancer ovarian samples than in normal ovarian samples." (PMID 39596024, 2024). "For instance, YBX1 is an interactive partner of lincNMR that regulates the expression of downstream RRM2, TYMS and TK1 by binding to their promoters, governing nucleotide metabolism and cell proliferation in cancer." (PMID 38491348, 2024). "TYMS and DHFR are the earliest 1C metabolism enzymes and clinical targets that have been successfully applied in cancer treatment." (PMID 38279895, 2024). "The newer generation of drugs selectively targeting key metabolic enzymes in SGOC metabolism, such as PHGDH, MTHFDs, DHFR, TYMS, GART and CBS, will provide a new strategy for cancer treatment in the future." (PMID 37147729, 2023). "Because decreasing TYMS in response to EPE diversifies the effect of EMT in more invasive CRC cancer cells, the previously reported diminished mobility and invasive ability of MPM cells upon EPE treatment is accomplished with TYMS downregulation as well." (PMID 37894370, 2023). "The results showed that the overexpression of TYMS promoted the proliferation of ESCC cells and tumor growth, which was consistent with the function of TYMS in other cancers." (PMID 37682862, 2023). "Considering the critical role of TYMS in cancer cell growth, proliferation and metastasis, for this paper we established, at the molecular level, the inhibitory effect of EPE on TYMS downregulation in mesothelioma cancer cells." (PMID 37894370, 2023). "In addition, TYMS regulates methyl group transfers that plays a role in nucleotide biosynthesis and folate-mediated one-carbon metabolism and thus dysregulation of these pathways by high levels of TYMS may result in aberrant DNA replication, increased DNA damage, chromosomal instability and cancer." (PMID 37106126, 2023). "Thymidylate synthase (TYMS) is involved in the malignant process of multiple cancers, and has gained much attention as a cancer treatment target." (PMID 37682862, 2023). "According to previous reports, the functions of CD44, ADM, TYMS, and MKI67 are primarily in promoting the Warburg effect and tumor growth in various cancers, while the function of those four genes in DTC has rarely been reported." (PMID 35528004, 2022). "As well as with oncogene expression, the decrease in MYC expression at 100 μg/mL, in TYMS at 500 μg/mL, and in MDM2 at 250 μg/mL was significantly lower than MTX as a commercial cancer drug." (PMID 35529172, 2022). "Numerous cancers have been treated with dihydrofolate reductase (DHFR) and thymidylate synthase (TYMS) inhibitors, such as methotrexate and pemetrexed." (PMID 36551330, 2022). "Our results stayed in agreement with the previous ones, which showed that downregulation of TYMS by siRNA resulted in a reversal of the EMT phenotype and inhibition of metastasis in various types of cancer." (PMID 35740289, 2022). "At this point, it is also worth suggesting a relationship between the level of TYMS expression and the EMT process in cancer cells." (PMID 35922756, 2022). "Consistent with this idea, upon grouping the DepMap cancer cell lines according to tissue origin, we noted that CDKN2A status and TYMP expression have varying effects on controlling TYMS dependency in different tumor types." (PMID 34454516, 2021).
cancer (continued). "Further studies on epigenetic modifications of the TYMS gene elucidating its metabolic regulation and related mechanisms will be useful, not only for developing new therapies for MPM but also for other cancers." (PMID 34646134, 2021). "This down-regulation of TYMS expression led to a decrease in cell viability in a dose-dependent manner in both HeLa and PC3 cancer cells." (PMID 32708710, 2020). "Anti-cancer agents targeting nucleotide biosynthesis pathways include a DHFR inhibitor (methotrexate) and a TYMS inhibitor (5-FU)." (PMID 31185958, 2019). "TYMS, SHMT2, and DHFR genes of one carbon metabolism are proven to contribute to genome instability and cancer development." (PMID 29312619, 2017). "Because both dTMP and deoxyribonucleotides are necessary for DNA replication and repair, inhibition of TYMS and RRM2 has been suggested to induce apoptosis in cancer cells." (PMID 28407751, 2017). "Because of the strong link between TYMS and deletions of 3p, 5q, and 6q - which are all linked to poor prognosis - separate subgroup analyses were also performed in cancers without these deletions, as well as in cancers harboring at least one of the three deletions." (PMID 25762627, 2015). "Increasing evidence has demonstrated that the expression levels of ERCC1, TYMS, TUBB3, RRM1 and TOP2A are closely correlated with the pathogenesis of carcinomas." (PMID 24926347, 2014). "Thymidylate synthase (TYMS) is an important folate-dependent enzyme in DNA synthesis and an important target for cancer chemotherapy." (PMID 23915286, 2013). "In fact, chemotherapeutic agents including methotrexate and 5-FU targeting dihydrofolate reductase (DHFR) and thymidylate synthase (TYMS), two important enzymes involved in one-carbon metabolism, have been clinically applied in treatment of several types of cancer including CRC." (PMID 34200820, 2021). "Another RNA-binding metabolic enzyme is thymidylate synthase (TYMS), a key target of cancer therapy that binds its own RNA in the absence of its substrate." (PMID 29216518, 2018). "TYMS downregulation has been found to increase oxidative stress production as well as activate protective pathways in multiple cancer lines but has not been extensively studied in neurons." (PMID 29955902, 2018). "With validations of experiments and HCC patients in multiple cohorts, we provided lines of evidence that TK1, TYMS and DTYMK the catalytic RLEs in pyrimidine biosynthesis play critical roles in cancer stemness and serve as potential therapeutic targets in poorly-differentiated HCC." (PMID 29100421, 2017). "The 5-FUDR parameter is not significantly affected by age, gender, cancer type, or polymorphisms in the MTHFR and TYMS genes." (PMID 26967565, 2016). "The expression level of TYMS exhibited a negative correlation with tumor invasion (r=−0.47, P=0.0098) and the clinical stage of carcinoma (r=−0.43, P=0.0191)." (PMID 24926347, 2014). "Furthermore, many genes in cancer-related pathways were also over-expressed in high CIN samples including proliferation (ASPM, CKS1B, MCM gene family, TOP2A, TTK, TYMS) and cancer testis antigens (MAGE family)." (PMID 23840451, 2013). "We also demonstrated that specific inhibitors of TYMS protein, such as raltitrexed, clearly showed cancer specificity, although we did not distinguish differential sensitivity among different tumour lines corresponding with the level of over-expression." (PMID 21365010, 2011). "Among them, we reported TYMP to be often deleted in several kinds of cancers but not in GC, while TYMS is frequently amplified, which may lead to treatment failure." (PMID 32887417, 2020).
cancer (continued). "However, given our data in this case and other reports by our group as well as by other investigators worldwide, we suggest that randomized studies should test the role of TYMS and DPD screening before 5-FU therapy in cancer patients to prevent an untoward toxicity, as more agents are available." (PMID 27774364, 2016). "A recent, large, prospective trial on cancer patients treated with 5FU monotherapy confirmed a significant––although weak––link between mutant MTHFR C677T genotypes and FU toxicity but, at odds with our results, also found a significant correlation with the 2R/2R TYMS genotype." (PMID 19384296, 2009). "However, TYMS, DUT, POLB, LIG1 and FEN1 have been identified by others as PARGi synthetic lethality genes, and these observations support the notion that inhibition of nucleotide biosynthesis and BER can sensitize cancer cells to pharmacological PARG inhibition." (PMID 39015544, 2024). "However, TYMS as a target of miR-197-3p in any type of cancer cell has not been studied." (PMID 35003215, 2021). "Indeed, CDKN2A and TYMS showed strong positive staining in a subset, but not in all cancer samples." (PMID 21365010, 2011). "Although the role of TYMS in ATC was not reported previously, the enzyme has been of interest as a target for cancer chemotherapeutic agents." (PMID 30774662, 2019). "A recently conducted pilot study concluded that TYMS expression and genotyping based on the 5′UTR repeats have no significant impact on the clinical outcome of cancer patients treated with 5FU." (PMID 22496803, 2012). "Not unexpectedly, TYMS (thymidylate synthase) was shown to be significantly upregulated in both EOC and fallopian adenocarcinoma relative to normal tissues but to approximately the same level when the two cancer types were compared." (PMID 23880844, 2013). "Even though this decreasing trend in the amplified transcription of SAMHD1 at 24 h might result in loosening the regulation of CAD, DHODH and UMPS, the critical enzymes involved in direct influx of dTMP (TYMS and TYMP) did not appear to be recovered to normal levels in cancer cells." (PMID 36414668, 2022).
tumor (234 papers, 2002 to 2026). "In group 1, high RFC‐1 and low TYMS expression were associated with better tumor response (p = 0.014 and p = 0.032, respectively)." (PMID 40357991, 2025). "High ABCC3 expression and low TYMS expression were significantly associated with better tumor response across the entire study cohort (p = 0.023 and p = 0.0009, respectively)." (PMID 40357991, 2025). "In group 1, an association was seen between low TYMS expression and stronger tumor response, and furthermore, low TYMS expression was significantly associated with better PFS." (PMID 40357991, 2025). "In group 2, high ABCC3 and low TYMS expression were associated with improved tumor response (p = 0.036 and p = 0.018, respectively)." (PMID 40357991, 2025). "Higher expression of miR-330 in tumor tissue has been associated with greater chemosensitivity, with TYMS being one of the targets." (PMID 39940936, 2025). "The TYMS expression is relevant to the sensitivity to 5-FU, and despite the demonstration of this functional association with fluoropyrimidine metabolism and tumor response in various studies, the effect of genetic polymorphism on TYMS is unclear." (PMID 39816293, 2024). "The 4 risk genes of LAMA4, POLA2, RAD51, and TYMS showed significant differences in the expression of normal and tumor tissues, and the 4 genes showed high expression in tumor tissues." (PMID 37051625, 2023). "Overexpression of TYMS is observed in a wide spectrum of tumor types, and elevated TYMS levels are associated with increased cellular proliferation, tumor invasiveness and metastasis, drug resistance, and poor clinical outcomes." (PMID 37097751, 2023). "The anti-tumor activities of 5FU and capecitabine are exerted by the irreversible inhibition of thymidylate synthase (TS), a cytosolic enzyme encoded by the TYMS (Thymidylate Synthetase) gene." (PMID 35922756, 2022). "It had been suggested that high expression of TYMS in various tumor types was associated with adverse reactions to TYMS targeted drugs." (PMID 33552145, 2020). "Low TYMS mRNA levels in CRC cells isolated from fresh specimens obtained after tumor resection were associated with in vitro resistance to 5-FU in those patients." (PMID 32933095, 2020). "With regards to the association of polymorphisms with the TNM staging system, only TYMS-28 3R/3R SNP was associated with decreased risk of tumor progression (OR = 0.55; 95% CI = 0.33–0.93; p = 0.023)." (PMID 33369477, 2020). "Q-PCR analysis showed that TYMS expression level was positively associated with TUG1 in clinical recurrent tumor samples." (PMID 31528224, 2019). "TYMS upregulation was significantly associated with unfavorable tumor phenotype, rapid tumor cell proliferation, and early PSA recurrence in our patients." (PMID 25762627, 2015). "Single gene analysis indicated that ERCC1 and TYMS expression levels were associated with the depth of tumor invasion, while TUBB3 expression was associated with the lymphatic metastasis of ESCC." (PMID 24926347, 2014). "The TYMS 1496 deletion polymorphism was associated with decreased mRNA stability and low expression in tumor tissue than the wild type polymorphism." (PMID 24278388, 2013). "Polymorphisms in the thymidylate synthase gene (TYMS) defines two risk groups associated with dissimilar tumor disease survival rates (60% vs. 22%)." (PMID 24212832, 2011). "Our data confirm the role of UGT1A1*28 variant as the most important in taking a decision and, for the first time, reveals TYMS 5′TRP polymorphism to be strongly related with tumour response in these patients." (PMID 20628391, 2010). "Moreover, CRISPR/Cas9-mediated TYMS knockout has been proposed as a strategy to increase tumor susceptibility to fluoropyrimidine-based treatments." (PMID 40496862, 2025). "However, genetic polymorphisms of TYMS and tumor heterogeneity contribute to 5-FU resistance in certain patients, diminishing the efficacy of chemotherapy." (PMID 39744483, 2025).